LINC01518 (long independently transcribed non-coding RNA 1518)
Synonyms: JINR1
Gene: Long non-coding RNA gene on chromosome 10 (42,644,445 to 42,691,745, reverse strand). Ensembl gene ENSG00000233515.
Diseases named in the same sentence as LINC01518 in open-access papers:
LINC01518 is named in the same sentence as 8 diseases in open-access papers, as found by Europe PMC text mining. Sharing a sentence is not in itself a finding about the gene and the disease. The quoted sentences say what the papers report.
esophageal squamous cell carcinoma (3 papers, 2025). Esophageal squamous cell carcinoma (ESCC) is a type of esophageal carcinoma (EC) that can affect any part of the esophagus, but is usually located in the upper or middle third. "Furthermore, LINC01063 has been identified as an oncogene in melanoma and an autophagy-associated lncRNA capable of predicting colorectal tumor prognosis, while LINC01518 has been shown to function as an endogenous competing RNA in esophageal squamous cell carcinoma." (PMID 40496210, 2025). "LINC01518 is overexpressed in oesophageal squamous cell carcinoma (ESCC) tissues, and it sponges miR-1-3p to promote the PIK3CA/Akt pathway to promote cell proliferation and inhibit apoptosis in ESCC cells." (PMID 40594481, 2025).
carcinoma (1 paper, 2025). A malignant tumor arising from epithelial cells. "Moreover, LINC01518 expression increases with advanced stages of carcinoma in HNSCC." (PMID 40594481, 2025).
tumor (1 paper, 2025). "We show that LINC01518 expression is significantly upregulated in high-grade HNSCC tumor samples in comparison to normal tissue, and transforming growth factor- β (TGF-β) promotes LINC01518 expression in HNSCC cell lines." (PMID 40594481, 2025). "The expression of Slug transcript is significantly increased in HNSCC primary tumor samples as compared to normal tissue, which is consistent with LINC01518 overexpression and miR-1-3p downregulation in HNSCC samples." (PMID 40594481, 2025). "We show that LINC01518 expression is elevated in high-grade HNSCC tumor samples." (PMID 40594481, 2025).
LINC01518 also shares sentences with these, for which no sentence is quoted: colorectal tumor (1 paper); head and neck squamous cell carcinoma (1); influenza infection (1); melanoma (1); viral infection (1).